PIK3CA (phosphatidylinositol-4,5-bisphosphate 3-kinase catalytic subunit alpha)
Diseases named in the same sentence as PIK3CA in open-access papers (continued):
Sharing a sentence is not in itself a finding about the gene and the disease.
colorectal cancer (continued). "Interestingly, cathepsin G in NETs was reported to kill PIK3CA-mutant colorectal cancer cells after being internalized via cell surface protein RAGE." (PMID 41480760, 2026). "Specifically, TIGAR contributes to ferroptosis resistance in colorectal cancer via the ROS/AMPK/SCD1 axis, while aspirin enhances RSL3-driven ferroptosis by inhibiting mTOR/SREBP-1 (sterol regulatory element-binding protein-1)/SCD1-regulated lipogenesis in PIK3CA-mutant colorectal cancer." (PMID 39935430, 2025). "Compared to existing molecular tools for colorectal cancer staging—such as APC, KRAS, BRAF, NRAS and PIK3CA mutations—our study offers a novel transcriptomic perspective by identifying stage-specific gene expression signatures that distinguish adenoma, CIS and adenocarcinoma." (PMID 40362431, 2025). "In PIK3CA-mutant colorectal cancer, GPT2 upregulation drives glutamine dependency." (PMID 41488637, 2025). "In this study, we aimed to evaluate the expression of SEMA7A, SEMA4D, ADAM8, and ADAMTS10 in colorectal cancer (CRC) in relation to the mutational landscape of KRAS, NRAS, BRAF, PIK3CA, and AKT genes, microsatellite instability (MSI) status, and clinicopathological features." (PMID 39329961, 2024). "Additionally, preclinical and clinical trial data have shown that the combination of CB-839 and capecitabine can effectively treat PIK3CA-mutant colorectal cancers." (PMID 39050886, 2024). "PIK3CA is considered to be an oncogene in the PI3K pathway in colorectal cancer." (PMID 38213716, 2024). "In addition, CB-839 upregulated the expression of UPP1 in various transplantation tumor models, strengthening the inhibitory effect of 5-FU on PIK3CA-mutant colorectal cancer." (PMID 38385072, 2024). "Some studies suggest that PIK3CA gene mutations are a negative prognostic factor for colorectal cancer patients, associated with lower overall survival (OS) and disease-free survival (DFS)." (PMID 39555098, 2024). "Similarly, mouse models with intestinal epithelial-specific PIK3CA mutations exhibit increased tumorigenesis, supporting the role of PI3K-Akt signaling in colorectal cancer development." (PMID 39161590, 2024). "Thirdly, the impact and mechanism of PIK3CA gene mutations on the treatment of colorectal cancer are not yet clear, especially in terms of their impact on immunotherapy." (PMID 39555098, 2024). "A study utilizing FISH identified PIK3CA amplification in 38% of colorectal cancer sample." (PMID 39555098, 2024). "However, a study conducted in colorectal cancer demonstrated that the CCDC6::RET fusion is mutually exclusive with other important driver mutations, such as KRAS, BRAF and PIK3CA." (PMID 39684377, 2024). "Although the functional relationship between PI3K/ATK signaling and MMR is not clear, enriched PIK3CA mutations were also observed in tumors with dMMR in colorectal cancer." (PMID 37920164, 2023). "An additional key observation of the current report is that BRAF mutated colorectal cancers with or without PIK3CA mutations display lower prevalence of APC mutations than colorectal cancers with wild type BRAF." (PMID 36079062, 2022). "The prognosis of BRAF mutated colorectal cancers with or without PIK3CA mutations is not significantly different than counterparts with wild type BRAF." (PMID 36079062, 2022). "In contrast, colorectal cancers with PIK3CA mutations but without BRAF mutations have statistically significant lower MSI, TMB, and CIMP rates and higher CIN rates compared with double mutants." (PMID 36079062, 2022).
colorectal cancer (continued). "Somatic hotspot mutations KRAS p.G12C and PIK3CA p.Q546K are associated with colorectal cancers from biallelic MUTYH carriers compared with non-carriers (p = 2 × 10−23 and p = 6 × 10−11, respectively)." (PMID 35668106, 2022). "The current investigation examines a panel of colorectal cancer cell lines with BRAF mutations with or without concomitant mutations in PIK3CA from the CCLE for drug sensitivities and molecular dependencies." (PMID 36295658, 2022). "However, for colorectal cancer patients receiving ICI treatments, the effect of PIK3CA mutations on prognosis is unclear." (PMID 35707003, 2022). "Despite preclinical data suggesting a possible improved response to cabozantinib in PIK3CA MT colorectal cancer tumors, there was no observed survival difference in subgroup analysis using PIK3CA mutational status." (PMID 36969746, 2022). "Compared with cell lines not bearing mutations in BRAF and PIK3CA, colorectal cancer cell lines with BRAF mutations with or without PIK3CA mutations show heterogeneous up-regulation in the mRNA expression of genes that are targets of the BRAF/MEK/ERK pathway." (PMID 36295658, 2022). "In contrast to KRAS mutations, mutations of the gene encoding for the catalytic sub-unit alpha of kinase PI3K, PIK3CA, which are common in colorectal cancer are not mutually exclusive with BRAF mutations." (PMID 36079062, 2022). "In contrast, no therapies targeting PIK3CA mutated colorectal cancers have been approved for clinical use." (PMID 36295658, 2022). "Mutations in the tumor suppressor APC are more prevalent in BRAF wild type colorectal cancers independently of the presence or absence of concomitant PIK3CA mutations in both cohorts (Fisher’s exact test p < 0.0001 for the comparisons in both cohorts)." (PMID 36079062, 2022). "Oncogene KRAS mutations are rather rare in BRAF mutant colorectal cancers, occurring in 10% of such cancers in TCGA and in about 5% in the DFCI cohort, compared with 37.8% and 31.6% in cancers with BRAF and PIK3CA wild type and 64.8% and 43.3% of cancers with BRAF wild type and PIK3CA mutations." (PMID 36079062, 2022). "Colorectal cancers with PIK3CA mutations are more often arising in the right colon and present with a higher mutation count than cancers without PIK3CA mutations." (PMID 36295658, 2022). "This was also observed in the DFCI cohort, where BRAF mutant colorectal cancers with or without concomitant PIK3CA mutations presented less often as stage III or IV than colorectal cancer with both genes on a wild type configuration." (PMID 36079062, 2022). "A high prevalence of MSI and CIMP is observed in BRAF mutated colorectal cancers with or without PIK3CA mutations." (PMID 36079062, 2022). "Considering the role of the PIK3CA gene and miRNAs, variation in 3’ UTR of this gene could increase susceptibility to colorectal cancer in the Chinese population." (PMID 35330456, 2022). "The aim of this study was to retrospectively analyze whether the PIK3CA and KRAS mutational status had an impact on overall survival in patients with colorectal cancer and aspirin use." (PMID 34638442, 2021). "The aim of this work was to examine whether PIK3CA mutational status and KRAS mutational status could indeed augment the effect of aspirin on the survival of patients with colorectal cancer." (PMID 34638442, 2021). "ETV5 may promote malignant progression of thyroid cancer through the PIK3CA signaling pathway, and ETV5 expression has also been associated with resistance to treatment with bevacizumab in colorectal cancer." (PMID 34335239, 2021).
colorectal cancer (continued). "And aspirin has a more significant therapeutic effect on PIK3CA mutant colorectal cancer." (PMID 32000660, 2020). "The findings of our study propose that PIK3CA mutation could be a predictive marker for the response to abemaciclib and BYL719 combination therapy in colorectal cancer treatment, and it should be validated in further preclinical and clinical trials." (PMID 32899250, 2020). "Four studies (involving 4346 patients) compared the overall survival of colorectal cancer among aspirin users compared with non-aspirin users among those with PIK3CA gene mutation." (PMID 32646396, 2020). "In a recent analysis on the use of gene variants and networks for drug repurposing in colorectal cancer, Irhan and collaborators discussed how to use colorectal cancer biomarkers, such as microsatellite instabilities (MSI), for the repurposing of PIK3CA modulators." (PMID 33520715, 2020). "Moreover, the most popular genes were APC (in Wnt pathway), KRAS (in MAPK pathway) and PIK3CA (in PI3K pathway) in the colorectal cancer, pancreatic cancer, and gastric cancer while they were beta-catenin and CTNNB1 in liver cancer." (PMID 33127962, 2020). "Two studies involving 2451 patients compared the cancer-specific survival in colorectal cancer among aspirin users compared with non-aspirin users among patients with a mutated PIK3CA gene." (PMID 32646396, 2020). "In colorectal cancer, aspirin use has been shown to improve survival among PIK3CA mutated cancers, but not PIK3CA wild type tumors." (PMID 32326897, 2020). "MAP2K1 mutation has been identified among subsets of smoking-associated lung carcinomas (mutually exclusive from EGFR, BRAF, KRAS, and NRAS mutations), lung adenocarcinoma in situ and early invasive disease, and KRAS/NRAS/BRAF/PIK3CA wild-type (“quadruple-wild-type”) colorectal carcinomas." (PMID 32483240, 2020). "Next, the most active derivatives were studied in MCF-7 (breast adenocarcinoma, Ras/RAF wild type, and PIK3CA mutant), HeLa (cervical carcinoma, Ras/RAF and PIK3CA wild type), as well as HCT-116 and HKH-2 (colorectal carcinoma, KRas mutant and mutated KRas disrupted, respectively) cell lines." (PMID 33371382, 2020). "Our findings might give additional insight into the relevance of the PIK3 pathway in colorectal cancer progression, and suggest that detailed genotyping of PIK3CA might be tailored to personalized medicine." (PMID 32099598, 2019). "Family history or inherited predisposition did not have any effect on the frequency of PIK3CA gene mutations in colorectal cancer." (PMID 31905960, 2019). "In addition, in a phase I study of the MEK inhibitor RO4987655, progressive disease was observed in patients with KRAS/PIK3CA-mutant colorectal cancer." (PMID 31769426, 2019). "Multiple kinds of cancer including thyroid cancer, prostate cancer, non-small cell lung cancer, glioma, colorectal cancer, chronic and acute myeloid leukemia, endometrial cancer and renal cell carcinoma seemed to affect by PIK3CA expression, some of which was demonstrated in a number of studies." (PMID 31472672, 2019). "Moreover, we will examine the enhanced the cell death by combined treatment with perifosine and trametinib or PD0325901 in other human colorectal cancer cell lines harboring KRAS, BRAF and PIK3CA mutation." (PMID 31769426, 2019). "Indeed, a previous report showed that mutations in various genes, including the tumor-suppressor gene PTEN and the oncogene PIK3CA, were caused by the instability of microsatellites in MSI-high colorectal cancers." (PMID 30458818, 2018).
colorectal cancer (continued). "We performed our investigation using the human PIK3CA mutant colorectal carcinoma HT29 and PTEN null prostate carcinoma PC3 cancer models as AKT signalling is involved in the tumourigenesis of colorectal and prostate cancers and AKT inhibitors are in clinical evaluation for both cancer types." (PMID 30377337, 2018). "As PIK3CA mutations often coexist with KRAS and BRAF mutations in advanced cancers, including colorectal cancers, combination of AKT inhibition with panRAF inhibition are expected to induce at a minimum additive effects in both KRASmut/PIK3CAmut and BRAFmut/PIK3CAmut CRC models." (PMID 27999210, 2017). "To test this concept further, we utilised two cell lines with basally high mTORC1 signalling: the NCI-H460 large cell lung cancer cell line which has PI3KCA, CDKN2A, STK11 and KRAS mutations and the HCT116 colorectal cancer cell line, which contains an activating RAS mutation and PIK3CA mutation." (PMID 28415776, 2017). "We investigated whether an inhibition of PIK3CA may decrease the CD26+ subpopulation within colorectal cancer cells." (PMID 28545226, 2017). "Of the 1001 consecutive colorectal cancer patients examined for RAS, PIK3CA, and BRAF tumor mutations using a multiplex kit (Luminex®), we studied 90 patients who received combination chemotherapy with bevacizumab as first-line treatment for metastatic colorectal cancer." (PMID 28068936, 2017). "The fact that STK11ex1-2 mutations were also associated with KRAS mutations might be related to a shared risk factor (tobacco) or an oncogenic cooperation between both alterations as for BRAF or KRAS with PIK3CA in lung and colorectal cancer." (PMID 26625312, 2017). "In addition, we also investigated critical molecular events such as KRAS, BRAF and PIK3CA mutations and MSI status, all of which have been associated with colorectal cancer prognosis in order to adjusted our results." (PMID 26515606, 2016). "Mutations in other genes, such as PIK3CA and NRAS may also influence anti-EGFR treatment efficacy in colorectal cancer." (PMID 25568935, 2015). "Regular use of aspirin after diagnosis is associated with longer survival among patients with mutated-PIK3CA colorectal cancer, but not among patients with wild-type PIK3CA cancer." (PMID 25388762, 2015). "In addition, we also investigated critical molecular events such as APC, KRAS, BRAF and PIK3CA mutations and MSI, all of which have been associated with colorectal cancer prognosis to justify the prognostic role of NEAT1." (PMID 26314847, 2015). "In addition, we also investigated critical molecular events such as KRAS, BRAF and PIK3CA mutations and MSI, all of which have been associated with colorectal cancer prognosis to justify the independent prognostic role of NDRG4." (PMID 25749388, 2015). "Colorectal cancers can be classified using mutations in oncogenes such as KRAS, BRAF and PIK3CA." (PMID 24885062, 2014).
colorectal cancer (continued). "Both PF-502 and PD901 exhibited single agent activity against in a large panel of colorectal cancer cell lines irrespective of RAS or PIK3CA mutational status." (PMID 25401499, 2014). "PIK3CA inhibitors may be beneficial in the treatment of colorectal cancer and decreases invasiveness of melanoma cells." (PMID 23768168, 2013). "Our data confirm that the sensitivity of PIK3CA mutant colorectal cancer to PI3K/mTOR inhibitors may depend on the presence of wild-type KRAS gene." (PMID 23826249, 2013). "Retrospective analyses in the West suggest that mutations in KRAS codons 61 and 146, BRAF, NRAS, and PIK3CA are negative predictive factors for cetuximab treatment in colorectal cancer patients." (PMID 24006859, 2013). "In contrast to KRAS, the heterogeneity of BRAF and PIK3CA mutations has not been adequately investigated in colorectal cancer thus far." (PMID 22931052, 2012). "In addition, none of the previous studies has comprehensively examined potential confounding effect of key molecular biomarkers in colorectal cancer, including the CpG island methylator phenotype (CIMP), and KRAS, BRAF and PIK3CA mutations." (PMID 21949851, 2011). "Far more possible, PIK3CA genetic changes may coparticipate in multi-step model of carcinogenesis pathway, likewise in the colorectal cancer, though these interactions require further evaluation." (PMID 20804548, 2010). "Colorectal cancer arises through a multistep carcinogenic process in which genetic and epigenetic alterations (e.g., microsatellite instability (MSI), CpG island methylation, mutations in KRAS, BRAF and PIK3CA) accumulate in a sequential manner." (PMID 20808308, 2010). "Similarly, comparing the survival of colorectal cancer patients with PIK3CA, FBXW7 and APC mutations/CNVs to all other patients without each of these mutations, only patients with concurrent PIK3CA mutations and CNVs had poorer survival outcomes." (PMID 41415395, 2025). "Moreover, the recognition that PTEN, PIK3CA, and ARID1A mutations are shared by endometrial, ovarian, and colorectal cancers provides a rationale for translational research that may benefit multiple patient populations." (PMID 40227624, 2025). "While genes like KRAS, APC, and PIK3CA maintain mutation frequencies relatively consistent with MSS colorectal cancer, the most significant observation is the markedly higher mutation frequency of DNA mismatch repair (MMR)‐related genes in MSI‐H colorectal cancer compared to MSS colorectal cancer." (PMID 38746969, 2024). "In conclusion, the current study shows that the complex landscape of BRAF mutated colorectal cancer with or without concomitant PIK3CA mutations offers several leads for therapeutic targeting to improve outcomes of this subset of metastatic cancer patients associated with adverse survival." (PMID 36079062, 2022). "In conclusion, targeted therapies of colorectal cancers that possess BRAF mutations with or without PIK3CA mutations could be developed based on the global molecular environment of these cancers and based on vulnerabilities uncovered in in vitro models." (PMID 36295658, 2022). "Consistently, in the DFCI cohort, the highest prevalence of MMR/proof-reading polymerases mutations is in double BRAF and PIK3CA mutant colorectal cancers with the exception of POLE which shows the highest mutation prevalence in BRAF mutant cancers without PIK3CA mutations." (PMID 36079062, 2022). "The colorectal cancers with PIK3CA mutation showed a higher TMB than nonmutated cancers." (PMID 35242279, 2022). "Interestingly, PIK3CA mutations do not feature among the molecular abnormalities conferring resistance to specific BRAF inhibitors in colorectal cancer cell lines." (PMID 36295658, 2022).